TREX1 (three prime repair exonuclease 1)
Diseases named in the same sentence as TREX1 in open-access papers (continued):
Sharing a sentence is not in itself a finding about the gene and the disease.
Aicardi-Goutières syndrome (continued). "Genetic factors including mutations in TREX1, a gene that encodes DNase III, have been seen in NPSLE patients among other diseases such as Aicardi-Goutieres syndrome, familial chilblain lupus, retinal vasculopathy, and cerebral leukodystrophy." (PMID 38893713, 2024). "Aicardi-Goutieres syndrome is classified as a monogenic interferon disease resulting from an aberrant mechanism involving intracellular nucleic acid sensing mediated by TREX1, RNASEH2A, RNASEH2B, RNASEH2C, SAMHD1, ADAR1 or IFIH1." (PMID 39286150, 2024). "Mice deficient in three prime repair exonuclease 1 (TREX1) accumulate cytosolic DNA, causing a lethal autoimmune disease that resembles Aicardi–Goutières syndrome in humans." (PMID 39254994, 2024). "Mutations that compromise TREX1 function are linked to autoinflammatory disorders, including systemic lupus erythematosus (SLE) and Aicardi-Goutières syndrome (AGS)." (PMID 38260344, 2024). "Autosomal recessive TREX1 gene defects have recently been linked to SLE, familial chilblain lupus, and Aicardi-Goutières syndrome (AGS)." (PMID 37622085, 2023). "For instance, mutations in IFIH1, TREX1, or ADAR1 can cause diseases such as systemic lupus erythematosus (SLE), Aicardi-Goutières syndrome (AGS), and multiple sclerosis (MS)." (PMID 37396372, 2023). "By using Trex1−/− mice, a mouse model of human Aicardi-Goutieres Syndrome and SLE, the importance of the cGAS signaling in autoimmunity has been well demonstrated." (PMID 34819357, 2022). "Loss of function mutations of TREX1, which were originally described in AGS (Aicardi Goutieres syndrome), result in accumulation of cytosolic DNA inducing a cGAS-dependent type I IFN secretion." (PMID 34381458, 2021). "Other types of type-I interferonopathies, such as systemic lupus erythematosus (SLE) and Aicardi–Goutières syndrome (AGS), have relationships with defective clearance of cytosolic nucleic acids caused by congenital dysfunction of TREX1, RNASEH2, and SAMHD1." (PMID 32411126, 2020). "TREX1 has been linked to a spectrum of diseases including SLE, lupus perniosis (Chilblain lupus), and Aicardi-Goutières syndrome (AGS)." (PMID 30116756, 2018). "TREX1, SAMHD1 and ADAR1 are known LINE‐1 repressors and when mutated cause the autoinflammatory disorder Aicardi‐Goutières syndrome (AGS)." (PMID 29959219, 2018). "Aicardi–Goutières syndrome (AGS), another form of early-onset SLE, is seen to be a monogenic form of lupus that brought light to the role of type I interferons and TREX1 gene mutations in SLE pathophysiology." (PMID 25999944, 2015). "Mutations in the protein three prime repair exonuclease 1 (TREX1), a major DNA exonuclease important in clearing endogenous DNA and antiretroviral infection, are responsible for Aicardi-Goutieres syndrome and familial chilblain lupus." (PMID 25077037, 2014). "Defective dsDNA digestion by TREX1 can lead to Aicardi-Goutières syndrome, systemic lupus erythematosus (neuropsychiatric SLE) and familial chilblain lupus." (PMID 23771145, 2013). "The pathogenic role of excessive type I IFN signaling is particularly evident in diseases such as Aicardi–Goutières Syndrome (AGS), where mutations in key nucleic acid regulatory proteins, such as TREX1 and ADAR1, lead to the aberrant accumulation of cytosolic nucleic acids." (PMID 40149865, 2025). "However, TBK1/IKKε inhibition by Compound II was shown to ameliorate autoimmune disease phenotypes in the Trex1-/- mouse model for Aicardi–Goutières syndrome, decreasing IFN gene signature and autoantibody titres as well as increasing survival." (PMID 40341181, 2025). "Moreover, MXC was shown to enhance survival in the Trex1−/− mouse model of Aicardi-Goutières syndrome." (PMID 41153813, 2025). "Thus, N-terminal TREX1 mutations result in hyperactivation of the cGAS-STING pathway, causing inflammatory diseases such as Aicardi-Goutières syndrome (AGS) and Familial chilblain lupus (FCL)." (PMID 41425849, 2025).
Aicardi-Goutières syndrome (continued). "Mutations in TREX1 (three prime repair exonuclease 1) or SAMHD1 (SAM domain and HD domain-containing protein 1), for instance, lead to the same autoimmune disease, Aicardi-Goutières syndrome (AGS)." (PMID 35058771, 2021). "The most prominent examples are mutations in Three-prime Repair Exonuclease 1 (TREX1) or Sam domain and HD domain 1 (SAMHD1), that are associated with the rare autoinflammatory disease Aicardi-Goutieres syndrome (AGS) characterized by an exaggerated type I IFN response." (PMID 29487579, 2018). "Autosomal recessive Aicardi-Goutières syndrome (AGS) and autosomal dominant familial chilblain lupus (FCL) are rare type I interferonopathies that can both result from loss-of-function variants in the TREX1 gene, which encodes a DNA exonuclease." (PMID 41194156, 2025). "Importantly, we demonstrate that MXC could promote the survival in Trex1–/– mouse model for Aicardi-Goutières syndrome (AGS)." (PMID 37120570, 2023). "Indeed, a recent report has demonstrated the accumulation of cytoplasmic L1-related ssDNAs in neurons derived from hESCs lacking the exonuclease TREX1, a gene mutated in Aicardi-Goutières syndrome patients." (PMID 30564290, 2018). "TREX1, SAMHD1 and ADAR1 are all negative modulators of LINE-1 and when mutated cause the autoinflammatory disorder Aicardi–Goutières syndrome (AGS)." (PMID 32244340, 2020). "Although DCs are activated by Type I IFNs, and might therefore become hyperactivated, and thus initiate the autoimmune process, phenotypic, or specific functional abnormalities of DCs in Trex1−/− mice or in patients with Aicardi–Goutières syndrome have not yet been reported." (PMID 23772226, 2013).
systemic lupus erythematosus (91 papers, 2011 to 2026). An autoimmune multi-organ disease typically associated with vasculopathy and autoantibody production. "Other variants within the TREX1 transmembrane segment, P290L, Y305C and G306A, associated with systemic lupus erythematosus variably modulated TREX1 proteolytic processing." (PMID 40072623, 2025). "Here, we show that Trex1 deficiency-induced endogenous DNA accumulation in CD4+ T cells greatly promoted their induction of autoimmune inflammation in a lupus-like mouse model." (PMID 39872301, 2023). "For example, mice deficient in the 3′ repair exonuclease encoded by Trex1 show severe systemic lupus erythematosus (SLE)-like symptoms." (PMID 35734577, 2022). "Heterozygous TREX1 mutations are associated with monogenic familial chilblain lupus and represent a risk factor for developing systemic lupus erythematosus." (PMID 35911727, 2022). "While homozygous loss of Trex1 results in AGS, heterozygous Trex1 loss-of-function alleles are associated with systemic lupus erythematosus (SLE), contributing to the polygenic predisposition for this severe autoimmune disease." (PMID 35634291, 2022). "Heterozygous mutations of TREX1 have been identified in patients with autoimmune disease such as systemic lupus erythematosus and Sjögren’s syndrome." (PMID 34997539, 2022). "This is different from Ifih1 mutants, which develop an antibody-mediated lupus-like nephritis, or from Trex1-deficient mice, which develop lupus-like inflammation in multiple organs." (PMID 34764281, 2021). "Familial chilblain lupus is a rare autosomal dominant form of cutaneous lupus erythematosus occurring mainly in young children, due to mutations in the TREX1 gene as well as in mutations within SAMHD1 or TMEM173 in rare cases." (PMID 34659260, 2021). "To date, four different DNases have been linked to monogenic lupus: DNase I, DNase1L3, DNase II and TREX1." (PMID 32151092, 2020). "Three prime repair exonuclease 1 (TREX1) has a 3′-5′ exonuclease activity and its mutations are associated with systemic lupus erythematosus." (PMID 32256502, 2020). "Familial chilblain lupus is a rare autosomal dominant monogenic form of lupus erythematosus based on heterozygous mutations in TREX1, SAMHD1, or STING." (PMID 31379837, 2019). "TREX1-deficient mice develop aberrant interferogenic responses and features of lupus owing to the cytoplasmic accumulation of endogenous nucleic acids and chronic activation of the TBK1-dependent DNA-sensing pathway." (PMID 29559975, 2018). "LINE-1 activity is upregulated in cells deficient for TREX1, a gene associated with systemic lupus erythematosus (SLE) and, like SAMHD1, with AGS." (PMID 26001115, 2015). "TREX1-deficient mice showed elevated production of type I interferon and lupus-like symptoms, which was demonstrated to be mediated by STING-dependent pathways." (PMID 25927578, 2015). "Heterozygous mutations in the TREX1 gene were observed in 9/417 patients with systemic lupus erythematosus (SLE) and in 1/169 subjects with Sjögren's syndrome (SS)." (PMID 24224166, 2013). "Heterozygous mutations in TREX1 were previously observed in patients with systemic lupus erythematosus (SLE) and Sjögren's syndrome (SS)." (PMID 24224166, 2013). "TREX1 mutations in humans lead to Aicardi-Goutieres syndrome, chilblain lupus and represent the more common cause of monogenic lupus." (PMID 22883345, 2012). "Thus, TREX1 and other interefonopathy variants are associated with chilblain lupus and CNS involvement." (PMID 40465409, 2025).
systemic lupus erythematosus (continued). "Conversely, as in the case of viral infections, we do not expect the SLC15A4-TASL complex to be involved in TLR7/9- and IRF5-independent autoinflammatory and autoimmune models, such as the lupus-like manifestations observed upon TREX1-deficiency which relies on the STING pathway." (PMID 39856058, 2025). "Accordingly, blocking the DNA sensing pathway in CD4+ T cells by genetic knockout of Zak or using our newly developed ZAK inhibitor iZAK2 attenuated all pathogenic characteristics in a lupus-like inflammation mouse model induced with Trex1-deficient CD4+ T cells." (PMID 39872301, 2023). "Indeed, most patients with lupus do not have monogenetic disease, with the most common form of monogenic lupus (mutations in the TREX1 gene) contributing to only 0.5 to 2% of adult lupus cases." (PMID 36585519, 2023). "Consistently, in vivo, administration of either iZAK2 or 2-DG could attenuate pathogenic characteristics in a lupus-like inflammation model induced with Trex1-/- CD4+ T cells." (PMID 39872301, 2023). "Further analyzing type I IFN-responding cell subtypes in monogenic types of lupus will help understanding the development of autoimmunity due to TREX1 mutations and will shed light on other types of SLE induced by similar disturbance in intracellular nucleic acid metabolism." (PMID 35911727, 2022). "Here, we describe a novel myeloid DC population enriched in lupus patients with TREX1 mutations." (PMID 35911727, 2022). "TREX1 loss-of-function alleles are also associated with systemic lupus erythematosus (SLE)." (PMID 35634291, 2022). "Moreover, It has been showed that cGAS activation causes lupus-like autoimmune disorders in a TREX1 mutant mouse model." (PMID 33468161, 2021). "Among the patients with a TREX1 mutation, 60% of subjects are documented to have at least one of the following lupus features: antibodies to extractable nuclear antigens (ENA), ANA and anti-dsDNA, thrombocytopenia, leukopenia, skin lesions, oral ulcers and arthritis." (PMID 32151092, 2020). "Familial chilblain lupus or TREX1-associated systemic lupus erythematosus is an autosomal dominant autoinflammatory disease caused by either loss-of-function mutations in TREX1 and SAMHD1 genes or gain-of-function mutations in the TMEM173 gene, both leading to type I IFN overproduction." (PMID 31736939, 2019). "Overactive TBK1 can precipitate IFN-Is and lupus, such as is the case for TREX1 deficiency." (PMID 29559975, 2018). "TREX1 deficiency in patients and murine models causes lupus-like autoimmune manifestations." (PMID 29559975, 2018). "Furthermore, TREX1 deficiency in lymphocytes modulates vascular EC angiogenesis, suggesting an interesting possible link between the genetic susceptibility for lupus associated with TREX1, ECs, and CNS disease." (PMID 24400009, 2013). "Indeed, systematic TREX1 mutation screening in adult lupus patients revealed 0.5 to 2% heterozygosity, thus making TREX1 mutations the most frequent form of monogenic lupus." (PMID 22883345, 2012). "Loss of TREX1 activity in humans and mice causes autoimmune diseases such as systemic lupus erythematosus (SLE) and Aicardi–Goutieres syndrome." (PMID 36964253, 2023). "Apart from AGS and FCL, mutations in TREX1 are also responsible for systemic lupus erythematosus (SLE)." (PMID 32293470, 2020). "Therefore, keeping cGAS-STING function in line could be a potential therapeutic strategy for the diseases caused by reduced TREX1 activity, such as lupus." (PMID 32180716, 2020). "Moreover, SIRT4 inhibitor treatment attenuates type I interferon signaling in Trex1-deficient cells and in peripheral blood mononuclear cells (PBMCs) from patients with systemic lupus erythematosus (SLE)." (PMID 41634380, 2026). "Previous animal studies using lupus-prone mice showed that pathogenic T cells drive spontaneous myocarditis development in MRL, MRL.lpr and Trex1-deficient mice, as well as resiquimod-induced autoimmune myocarditis in CFN mice." (PMID 41203999, 2025).
systemic lupus erythematosus (continued). "Trex1 mutations are also associated with the autoimmune disease systemic lupus erythematosus (SLE)." (PMID 39254994, 2024). "To date, four different DNases, DNase I, DNase1L3, DNase II, and DNase III, also called TREX1, have been linked to monogenic and early-onset lupus." (PMID 38357265, 2023). "TREX1 variants are associated with autoimmune and inflammatory diseases, including AGS, familial chilblain lupus, systemic lupus erythematosus, and retinal vasculopathy with cerebral leukodystrophy." (PMID 36814213, 2023). "TREX1 deficient mice succumb from autoimmune myocarditis, type I IFN upregulation and cutaneous lesions reminiscent of lupus." (PMID 35911727, 2022). "TREX1 loss of function or dominant negative mutations have been reported in AGS, familial chilblain lupus and systemic lupus erythematosus patients." (PMID 33888553, 2021). "Loss of function mutations in TREX1 and gain-of-function mutations of IFIH1 are both known to cause lupus-like phenotypes in humans and animal models, while both are involved in the pathways that activate IRF3." (PMID 32719713, 2020). "TREX1 deficiency and mutations have been implicated in Aicardi-Goutieres syndrome (AGS), Familial chilblain lupus, systemic lupus erythematosus (SLE) and retinal vasculopathy with cerebral leukodystrophy (RVCL)." (PMID 33552072, 2020). "Selective pharmacological JAK1 inhibition significantly reduces the expression of typical proinflammatory mediators such as CXCL chemokines, BLyS, TRAIL, and AIM2 in CLE in vitro models and also improves skin lesions in lupus-prone TREX1–/– -mice markedly." (PMID 32194562, 2020). "An evaluation of TREX1, a 3′–5′ exonuclease associated with SLE, revealed a common risk haplotype in lupus patients with brain manifestations, particularly seizures." (PMID 29928273, 2018). "Many genes have been identified as causes of monogenic lupus and at the same time have been associated with common forms of SLE, such as C4 number variation and polymorphisms in TREX1, among others." (PMID 30459768, 2018). "Trex1 deficiency or mutation, on the other hand, is associated with systemic lupus erythematosus (SLE), chilblain lupus and the human disease Aicardi-Goutières syndrome (AGS) and in this case inflammation is initiated from non-haematopoietic cells via a STING-dependent pathway." (PMID 23251783, 2012). "Mutant TREX1-dsDNA―cGAS―STING―spontaneous lupus-like inflammatory." (PMID 41153813, 2025). "Here, we showed that the overactivated DNA sensing through the KU-ZAK system in Trex1–/–CD4+ T cells greatly enhanced the glycolysis, thereby leading to sever pathogenic symptoms in an inducible lupus-like inflammation model, which is a novel mechanism for accumulated DNA in pathogenesis in SLE." (PMID 39872301, 2023). "In addition, mutations in Trex1 have previously been shown to be highly relevant to familial chilblain lupus (FCL), retinal vasculopathy with cerebral leukodystrophy (RVCL), and systemic lupus erythematosus (SLE)." (PMID 36545321, 2022). "TREX1 mutations are detected in about 25% of AGS patients, and in up to 2% of patients with lupus." (PMID 32151092, 2020). "Remarkably, heterozygous mutations in TREX1 represent the single most common cause of monogenic lupus and mice lacking Trex1 develop a severe multiorgan autoimmune disease that is driven by IFN from non-hematopoietic cells." (PMID 25077037, 2014). "Autoimmune diseases in Trex-1 and DNase II-deficient mice were shown to be dependent on the cGAS-STING pathway, and other murine studies have demonstrated the contribution of the cGAS-STING pathway to enhancing type I IFN responses in lupus or lupus-like mouse models." (PMID 40746538, 2025).